ARID3A (AT-rich interaction domain 3A)
Diseases named in the same sentence as ARID3A in open-access papers (continued):
Sharing a sentence is not in itself a finding about the gene and the disease.
pancreatic cancer (2 papers, 2025). "Clinically, high expression of IRP1 and ARID3A associates with unsatisfactory chemotherapeutic response and poor survival of patients with pancreatic cancer." (PMID 42290659, 2025). "The study uncovers the important role of ARID3A in pancreatic cancer, particularly in enhancing chemoresistance by inhibiting PTEN-induced ferroptosis." (PMID 40733146, 2025). "A recent study demonstrated that the knockout of the transcription factor AT-rich interactive domain-containing protein 3A (ARID3A) can inhibit tumor progression in pancreatic cancer and enhance the sensitivity of cells to gemcitabine." (PMID 40733146, 2025). "Thus, ARID3A inhibition to promote PTEN-mediated ferroptosis offers a new approach for pancreatic cancer chemoresistance." (PMID 40733146, 2025). "Here, we demonstrate that high expression of iron-responsive element binding protein (IRP1)/A + T rich interaction domain protein 3a (ARID3A) inhibits ferroptosis and enhances chemoresistance of pancreatic cancer cells via handling the promoter region of a ferroptosis gene, cytoglobin (CYGB)." (PMID 42290659, 2025).
periodontitis (2 papers, 2023). An acute or chronic inflammatory process that affects the tissues that surround and support the teeth. "In addition, we discovered TFs, E2F3, ELL and ARID3A are up-regulated in periodontitis tissues compared with the healthy control, however, there was no statistical significance, there may be shortcomings of small sample size." (PMID 37495990, 2023).
adenoma (1 paper, 2015). A neoplasm arising from the epithelium. "To gain insight into the association of several Let-7 targets with tumorigenesis in vivo, we examined Hmga1, Hmga2, Arid3a, and Hif3a protein expression by immunostaining adenomas and adenocarcinomas, as well as adjacent normal tissue, from Lin28bLo/Let7IEC-KO mice." (PMID 26244988, 2015).
alcoholism (1 paper, 2020). "We were able to recapture findings from previous studies by showing that ARID3A is involved in regulating a network of genes found in pathways of SLE and alcoholism." (PMID 32459338, 2020).
autoimmune disease (1 paper, 2019). A disorder resulting from loss of function or tissue destruction of an organ or multiple organs, arising from humoral or cellular immune responses of the individual to their own tissue constituents. "ANA production in ARID3a-transgenic mice was observed on two genetic backgrounds and was associated with increases in transitional T1 B cells and MZ B cells, subsets previously associated with autoimmune disease activity in mice and humans." (PMID 31554207, 2019). "Nothing is known regarding the function or expression of ARID3a in other autoimmune diseases." (PMID 31554207, 2019).
autoimmune hepatitis (1 paper, 2023). Hepatitis caused by autoantibodies. "IHC staining of the diagnostic liver biopsy showed that the expression of ARID3A in the portal area of PBC was significantly increased, compared with autoimmune hepatitis (AIH), chronic hepatitis B (CHB) and HCs." (PMID 36977669, 2023).
B-cell acute lymphoblastic leukemia (1 paper, 2021). A neoplasm of lymphoblasts committed to the B-cell lineage, typically composed of small to medium-sized blast cells. "In B-ALL (B-cell Acute Lymphoblastic Leukemia), ARID3a is targeted by miR-125b, where ARID3a inhibits differentiation, increases proliferation and inhibits apoptosis." (PMID 33412518, 2021).
Cholestatic liver disease (1 paper, 2025). "The transcription factor Arid3a inhibits Mertk expression to minimize macrophage efferocytosis in cholestatic liver disease." (PMID 41332347, 2025).
cholesteatoma (1 paper, 2022). A pathologic process characterized by the proliferation of keratinizing squamous epithelium resulting in the accumulation of keratin and cells in the middle ear and/or mastoid. "However, in our own middle ear expression dataset from the same patients, all 12 genes were DEGs for cholesteatoma: RTN4, RAB5A, CRYBG1, RGS22, HEPHL1, and SPTLC3 were upregulated, while APBB1IP, BHLHE41, ARID3A, C5AR1, CPT1B, and FAM227A were downregulated." (PMID 36699445, 2022).
COVID-19 (1 paper, 2024). A disease caused by infection with severe acute respiratory syndrome coronavirus 2. "It is also reported that in COVID-19 asymptomatic patients, ARID3A is strongly associated with IFN or IFN receptors suggesting the importance of this TF." (PMID 38365632, 2024).
gastric cancer (1 paper, 2016). A primary or metastatic malignant neoplasm involving the stomach. "In our study, we found that ARID3A was upregulated in gastric cancer compared with normal tissues." (PMID 27403158, 2016). "Therefore, we speculated that ARID3A may act as an oncogene in the development of gastric cancer." (PMID 27403158, 2016).
Hypertension (1 paper, 2024). The presence of chronic increased pressure in the systemic arterial system. "In conclusion, these results indicate that mRNAs KIAA0513, LRPAP1, ARID3A, and hsa-miRNA-5589–5p can be considered as diagnostic biomarkers for patients with hypertension." (PMID 38836231, 2024). "Among these mRNAs, ARID3A, LRPAP1, and KIAA0513, along with hsa-miRNA-5589–5p, demonstrated associations with hypertension." (PMID 38836231, 2024). "While miRNA-mRNA networks have previously been utilized to detect markers for various diseases, including hypertension, the regulatory networks involving LRPAP1, KIAA0513, and ARID3A have been less explored." (PMID 38836231, 2024). "ARID3A, a member of the ARID family, is applied as a bimolecular target for drugs in order to treat diseases, particularly hypertension." (PMID 38836231, 2024). "Additionally, public data revealed that CEBPA binding peaks were present upstream of LRPAP1 and ARID3A, strengthening the possibility of CEBPA’s regulatory role in hypertension." (PMID 38836231, 2024). "Notably, this analysis revealed that LRPAP1, ARID3A, and KIAA0513 may have the potential to influence hypertension." (PMID 38836231, 2024).
kidney tumors (1 paper, 2015). "ARID3B is increased in kidney tumors compared to normal kidney while ARID3A decreases." (PMID 26121572, 2015).
liver diseases (1 paper, 2023). "To determine whether ARID3A is expressed differentially in PBC, we quantified its expression in liver samples from patients of different liver diseases and healthy controls (HCs)." (PMID 36977669, 2023).
lupus erythematosus (1 paper, 2020). An autoimmune, connective tissue chronic inflammatory disorder affecting the skin, joints, kidneys, lungs, heart, and the peripheral blood cells. "ARID3a expression in circulating peripheral blood HSPCs from lupus erythematosus patients is upregulated compared to similar cells from healthy individuals, although the role of ARID3a in those cells is unknown." (PMID 32905435, 2020).
migraine (1 paper, 2026). "Through structure-guided drug repurposing, we identified the clinically approved migraine agent rimegepant as an ARID3A-targeting small molecule." (PMID 42230325, 2026).
nephritis (1 paper, 2019). Inflammation of renal tissue. "While there is no direct evidence that ARID3a is associated with the development of nephritis in SLE patients, there are a number of interesting observations that suggest it could be." (PMID 31554207, 2019).
pulmonary artery hypertension (1 paper, 2022). "In addition, ARID3A levels which are increased in patients with pulmonary artery hypertension (PAH), were also found increased in cells with a diminished expression of PCAT14." (PMID 36338971, 2022).
rectal cancer (1 paper, 2020). A primary or metastatic malignant neoplasm that affects the rectum. "ARID3A (AT-rich interactive domain 3A) positivity was implied to be correlated with longer DFS and cancer-specific survival in patients with residual rectal cancer." (PMID 32149080, 2020).
rheumatoid arthritis (1 paper, 2019). A chronic, systemic autoimmune disorder characterized by inflammation in the synovial membranes and articular surfaces. "To determine if ARID3a was over-expressed in lupus B lymphocytes, we assessed the numbers of peripheral blood B cells for ARID3a expression in healthy controls, patients with rheumatoid arthritis, and SLE patients." (PMID 31554207, 2019). "In a limited patient sample, we did not observe ARID3a over-expression in the B lymphocytes of patients with rheumatoid arthritis." (PMID 31554207, 2019).
small cell carcinoma of the ovary (1 paper, 2015). "Moreover, ARID3A and SMARCA4, recently found to be mutated in small cell carcinoma of the ovary, are both located on the short arm of chromosome 19, which is recurrently deleted in 29/80 and 18/80 SS genomes, respectively." (PMID 26415585, 2015).
stomach tumor (1 paper, 2015). "Conversely, ARID3A is increased in stomach tumors compared to normal stomach; ARID3B decreases during stomach tumor progression." (PMID 26121572, 2015).
tumor (20 papers, 2007 to 2026). "Here, we identify the transcription factor ARID3A as a tumor-intrinsic regulator of this resistant state." (PMID 42230325, 2026). "To assess the clinical relevance of NRF2 pathway activation in OAC primary tumours, we employed four NRF2 targets (KIAA0319, ARID3A, HSPA1B, PTGR1) from clusters 2 and 9 to calculate the risk score based on datasets from The Cancer Genome Atlas (TCGA)." (PMID 40473905, 2025). "ARID3A, member of AT-rich interaction domain (ARID) family, is a transcriptional factor that has been already implicated in HCC, up-regulated in tumor samples, partly due to DNA demethylation at its gene locus, and related to a poor outcome." (PMID 39858538, 2025). "ARID3A promotes tumor growth by interacting with CEP131 to promote the expression of stem cell-like genes." (PMID 39590360, 2024). "In the TWM cases, except case 1, ARID3A, ASXL1, ASXL2, FMN2, FAM83B and ZFHX4 mutations were also identified as potential oncogenic drivers, known from other tumor types." (PMID 36980598, 2023). "Cells with stable ARID3A-overexpression generated from Huh7 cells were subcutaneously injected into nude mice, and the weights of the tumours were found to be much higher in the ARID3A-overexpressing group than in the control group." (PMID 36008383, 2022). "In contrast, a recent study showed that the expression of ARID3A assures megakaryocytic differentiation and growth restriction, playing a tumour suppressor role in AMKL." (PMID 36008383, 2022). "Genetic ablation of ARID3A inflamed the tumor microenvironment, enhanced dendritic-cell activation, increased antigen-specific tetramer-positive and total CD8+ T-cell infiltration with heightened cytotoxic activity, and sensitized otherwise resistant tumors to PD-1 blockade in vivo." (PMID 42230325, 2026). "This study also illustrated that hypoxia induced tumor derived exosomal HMMR-AS1 could affect the regulation of ARID3A-mediated M2 polarization of macrophages or macrophages infiltration by targeting miR-147a." (PMID 39928285, 2025). "The Knockdown of ARID3A could promote M1‐type polarization and inhibit M2‐type polarization, thus inhibiting tumour cell proliferation and metastasis." (PMID 38501838, 2024). "Moreover, patients with a poor histologic grade, metastasis and tumour thrombus had higher expression of ARID3A." (PMID 36008383, 2022). "Interestingly, immunohistochemical (IHC) analysis of the xenografts showed that the ARID3A-positive cells were mainly located at the periphery of the tumour, indicating that ARID3A is related to cell stemness regulation in vivo." (PMID 36008383, 2022). "ARID3A is a DNA conjugation protein that negatively regulates tumor cell metastasis and invasion." (PMID 34843038, 2022). "ARID3A was prevalent high-expressed in tumour tissues of digestive cancers." (PMID 35127746, 2021). "Therefore, we suspected that tumor progression of the ABC subtype DLBCL is promoted through miR-129-5p/ARID3A-mediated activation of the JAK/STAT pathway." (PMID 34778251, 2021). "Further mechanistic investigations revealed that the knockout of ARID3A alleviates transcriptional repression of PTEN, which is a known tumor suppressor." (PMID 40733146, 2025). "ARID3A showed a strong negative correlation with a wide range of immune tumour-infiltrating cells in COAD microenvironment." (PMID 36582202, 2022). "In addition, previous research has shown that ARID3A and ARID3B jointly regulate gene expression in B-cells and cancers, regulate stem cell-related genes, and promote the phenotype of tumor stem cells." (PMID 36034939, 2022). "The mRNA expression of ARID3A, ARID3B, ARID4B, JARID1B, JARID1C, JARID2 in tumor tissues was more expressive in normal tissues, ARID1B, ARID3C, ARID4A, ARID5A, ARID5B, JARID1A mRNA expression in tumor tissues were lower than that in the normal tissues (p<0.05)." (PMID 33592583, 2021).
tumor (continued). "Specifically, we clarified that the miR-29-5P/ARID3A axis constitutes a negative feedback loop, which modulates PD-L1 expression in DLBCL and leads to changes in CD8+ T cell activity, ultimately promoting the immune escape of tumor cells." (PMID 34778251, 2021).
cancer (18 papers, 2014 to 2025). A tumor composed of atypical neoplastic, often pleomorphic cells that invade other tissues. "The miRNA Let-7 may regulate ARID3a expression in some cell types, and the dysregulation of Let-7 has been associated with a number of different cancers, where ARID3a expression might also occur." (PMID 31554207, 2019). "The ARID3A oncogene is transcribed from an alternative promoter located in a TE (transposable element) across 15 cancer types, as demonstrated in a previous study by analysis of CAGE-seq data." (PMID 36008383, 2022). "AT-rich interactive domain 3A (ARID3A) was considered as an independent prognostic predictor for several cancers." (PMID 35125116, 2022). "Taken together, these data suggest that ARID3A promotes cancer cell viability and metastasis both in vitro and in vivo." (PMID 36008383, 2022). "In this study, we identified the regulation networks between the PRSGs and key TFs (EPO, ARID3A), hallmarks of cancer gene sets (DNA repair, myc targets, E2F targets, mTORC1 signaling, and unfolded protein response)." (PMID 33816287, 2021). "ARID3A is necessary for fetal B lymphopoiesis and B1 cell division, and has also been shown to promote cancers by driving higher MYC expression." (PMID 33679795, 2021). "In cancer cells, ARID3A and ARID3B recruit histone demethylase 4C (KDM4C) to make a tri-protein complex, called the ARID3B complex." (PMID 32455665, 2020). "Levels of HMGA1, HMGA2, PLAGL2, IGF2BP2, E2F5, and ARID3A transcripts were also inversely proportional to levels of Let-7 miRNA by examination of a cohort of 199 CRC patients from the TCGA Pan-Cancer analysis project." (PMID 26244988, 2015). "Human ARID3A is also one of the targets of the broad Human Cancer Protein Interaction Network (HCPIN) database, which aims to provide structure-function annotations of key proteins related to cancer diseases and developmental biology." (PMID 25187961, 2014). "It was discovered in 91 cases that ARID3A positive was associated with absence of perineural invasion, longer disease-free life, and longer cancer-specific survival." (PMID 35402625, 2022). "Notably, ARID3A showed the highest correlation (in terms of the correlation coefficient (r)) with stem cell characteristics, indicating that dysregulation of ARID3A may play a key role in cancer development and progression." (PMID 36008383, 2022). "Our analysis revealed that genes such as ARID3A, CCNA2, and DDX39A were consistently and significantly overexpressed in cancer tissues." (PMID 40735323, 2025). "Also, overexpression of ARID3A could potentiate cancer cell proliferation, migration, and invasion." (PMID 36034939, 2022). "Numerous other genes such as ESPL1, DOCK8, ARID3A, PFKFB4, ANKZF1, BANP and GRB7 showed elevated expression rates, some of which are known or suspected to be involved in cancer development and/or progression." (PMID 37193047, 2022). "ARID3A, a member of ARID family of DNA-binding proteins, serves as an independent predictor for prognosis in various cancers." (PMID 33816287, 2021). "Moreover, we found two key TFs (EPO, ARID3A), four key PRSGs (CACNA1E, LINC01356, CGA and SSX3) and five key hallmarks of cancer gene sets (DNA repair, myc targets, E2F targets, mTORC1 signaling and unfolded protein response) in the regulatory network." (PMID 33816287, 2021). "ARID3A inhibits cell differentiation, promotes cell proliferation, and increases survival potential of cells, whereas ARID3B promotes proliferation, invasion, and migration of cancer cells." (PMID 32455665, 2020).
infection (4 papers, 2015 to 2023). The state of being infected such as from the introduction of a foreign agent such as serum, vaccine, antigenic substance or organism. "As we analyze the TFs that belongs to each time of infection evaluated, we found that at 24-hpi, more than half of TFs are related to an M1 phenotype in humans and mouse, and also were upregulated in our results, corresponding to ARID3A, IRF1, MXD4, and BNC1." (PMID 38162669, 2023). "Among the highly upregulated genes in both infection groups were ESPL1, DOCK8, ARID3A, PFKFB4, ANKZF1, BANP and GRB7, all of which exhibited a log2 fold change of ≥1.5." (PMID 37193047, 2022).
ARID3A also shares sentences with these, for which no sentence is quoted: esophageal squamous cell carcinoma (3 papers); Obesity (2); primary biliary cholangitis (2); abdominal aortic aneurysm (1); adenocarcinoma (1); allergic respiratory disease (1); B-Cell Lymphomas (1); basal cell carcinoma (1); cardiovascular diseases (1); chronic hepatitis B (1); chronic liver failure (1); clear cell carcinoma (1); diabetes (1); diffuse large B-cell lymphoma (1); esophagus neoplasms (1); gastric adenocarcinoma (1); heart failure (1); hematological diseases (1); hepatocellular adenoma (1); myocardial infarction (1); myocardial ischemia (1); nasopharyngeal carcinoma (1); otitis media (1); renal fibrosis (1); respiratory disorders (1).